BRAF (B-Raf proto-oncogene, serine/threonine kinase)
Diseases named in the same sentence as BRAF in open-access papers (continued):
Sharing a sentence is not in itself a finding about the gene and the disease.
melanoma (continued). "The prognostic value of ctDNA levels was also demonstrated in a phase II cohort of melanoma patients which included histologically confirmed patients with BRAF mutant stage IV melanoma." (PMID 28484715, 2017). "In this context, it has previsouly been shown that the PDK inhibitor DCA negatively affects the growth of melanoma cells, which are sensitive or resistant to BRAF inhibition by suppressing glycolysis." (PMID 28595656, 2017). "Among the 12 patients with BRAF mutant melanoma who received BRAF/MEK inhibitors, median duration on therapy was 8.0 months – suggesting that these therapies retain their efficacy in patients who progress on HD IL-2." (PMID 28923120, 2017). "Another study performed a SL RNAi screen in BRAFV600E‐mutant melanoma found that BRAF inhibition combined with ROCK1 silencing leads to cell death." (PMID 28097822, 2017). "Oncolytic immunotherapies, immune checkpoint inhibitors, and cytokines have been evaluated in melanoma, as have targeted therapies from the BRAF and MEK inhibitor classes (including combinations)." (PMID 29928546, 2017). "Consistently, the upregulation of EGFR in melanoma cells results in loss of activity of BRAF inhibitors and dual inhibition of EGFR and BRAF re-establishes vemurafenib activity in colon carcinoma cells." (PMID 29033690, 2017). "Similar efficacy is observed with BRAF and MEK inhibitors in BRAF mutated melanoma cells through induction of ER stress when combined with BRAF inhibition." (PMID 29254276, 2017). "Accelerated approval of the combination for BRAF-mutant melanoma was granted by the FDA in January 2016." (PMID 29179523, 2017). "Our in vitro drug studies confirmed that high level of HGF/MET signaling correlates with low sensitivity to a BRAF(V600E) inhibitor in melanoma." (PMID 28453553, 2017). "First, using the pan‐EDNR inhibitor Bosentan, they show that combination treatment with BRAF inhibitor is more effective in interfering with the growth of melanoma xenografts than either single treatment." (PMID 28694322, 2017). "The design of this experiment was the following: four BRAF-mutated melanoma cell lines (A375, SKmel28, HT144 and WM266-4) and one BRAF-WT cell line (SKmel23) were treated with increasing doses of vemurafenib for 96h." (PMID 29299138, 2017). "RNF125, as a little studied E3 ubiquitin-protein ligase, was recently reported to play a promoting role in lymph node metastasis of colorectal cancer; its expression downregulation was correlated with resistance of melanoma cells to BRAF inhibitors." (PMID 28611292, 2017). "Alternate BRAF splicing is the most common mechanism of acquired resistance to BRAF inhibitor treatment in melanoma." (PMID 28503307, 2017). "In the clinic, BRAF inhibition has improved metastasis of melanoma, and during treatment, tumors exhibited a significant increase in CD8+ T cells, which is linked to the down regulation of vascular endothelial growth factor (VEGF) and IL-6, IL-1α cytokines." (PMID 28878676, 2017). "Inhibition of ERK pathway in melanoma cells with BRAF inhibitors results in cell cycle arrest and promotes cell death including apoptosis." (PMID 28830513, 2017). "After 72 h of exposure, CDK4 inhibitor palbociclib reduced melanoma cell proliferation of Ma-Mel-123 cells with significantly higher efficiency than BRAF inhibitor vemurafenib (p = 0.0017)." (PMID 27903987, 2017). "To further elucidate the prognostic impact of mutations in the BRAF and NRAS genes, we analyzed the genotype of 217 patients with melanoma and retrospectively correlated the mutation status to primary tumor and clinical data." (PMID 28797232, 2017). "Activating BRAF mutations and the loss of the tumor suppressor PTEN are events with a significant co-occurrence in melanoma." (PMID 28753606, 2017). "Targeted therapies specific to the BRAF-MEK-ERK signaling pathway have shown great promise in the treatment of malignant melanoma in the last few years, with these drugs now commonly used in clinic." (PMID 28811486, 2017).
melanoma (continued). "We retrieved randomized controlled trials testing immune, BRAF‐ or MEK‐targeted therapies for advanced melanoma from electronic databases." (PMID 28463413, 2017). "Melanoma patients with metastatic or unresectable disease, according to recent NCCN guidelines, should be tested for BRAF V600 mutations to evaluate therapy options." (PMID 28039443, 2017). "We had previously detected increased macrophage abundance in BRAFV600E-positive melanomas from patients that had been treated with BRAF and MEKi for 10–14 d." (PMID 28450382, 2017). "Currently mainly BRAF mutant circulating tumor DNA (ctDNA) is utilized to monitor patients with melanoma." (PMID 29108273, 2017). "We show that targeting these communications by inhibiting EDNR signalling suppresses aggressive melanoma phenotypes and has the potential to improve the outcome of BRAF inhibitor therapy." (PMID 28606996, 2017). "Overall, a 14% partial response and 27% stable disease rate in patients with wild-type (serine/threonine-protein kinase B-raf) BRAF melanoma was observed." (PMID 28621712, 2017). "Previously, it has been mentioned that ER stress induced by BRAF inhibitor triggers autophagy for melanoma cell survival." (PMID 28629173, 2017). "Those pieces of evidences suggest that BAG3 protein is involved in one of the major mechanism that sustain melanoma cells growth id est the axis BRAF/MEK/ERK." (PMID 29113311, 2017). "For example, these inhibitors retain cytotoxicity in cultured melanomas resistant to BRAF inhibitors." (PMID 28484090, 2017). "Vemurafenib is effective against BRAF mutant melanomas but resistant cells often result in recurrence of metastases." (PMID 37133296, 2017). "Patients with BRAF positive melanomas were significantly younger (dichotomized into those ≤50 vs >50 years of age) as compared to patients with BRAF wild type melanoma (p = 0.035)." (PMID 28662062, 2017). "In contrast, BRAF wild type melanomas develop at an older age, reveal a thin meshwork pattern and junctional thickening." (PMID 28662062, 2017). "Arozarena had previously demonstrated that BRAF V600E increases the levels of BRN2 (a transcriptor factor) in melanoma cells, which is responsible for invasiveness." (PMID 27738305, 2017). "BRAF inhibitors (BRAFi) and the combination therapy of BRAF and MEK inhibitors (MEKi) were recently approved for therapy of metastatic melanomas harbouring the oncogenic BRAFV600 mutation." (PMID 29050198, 2017). "By blocking BRAF production in metastatic melanoma cells and by forcing MAP2 to be expressed via demethylation by decitabine, we can induce apoptosis." (PMID 29179510, 2017). "In this retrospective study, a survival benefit of >10% was recorded for our procedure in wild type BRAF melanoma patients, suggesting a potentially important survival benefit." (PMID 29120401, 2017). "Although clinical validation is lacking, our results argue against the use of vitamin A supplementation in melanoma patients undergoing treatment with BRAF inhibitors, due to the potential antagonizing effect." (PMID 29137417, 2017). "The RAF kinase, BRAF, plays an important role in MAPK signaling, and activating mutations of the BRAF gene are detected in 48–69% of melanoma cases." (PMID 29176861, 2017). "Vemurafenib acts by targeting the most common genetic alteration in melanomas, BRAF V600E, and thus it suppresses the RAS/MEK/ERK signalling pathway and accordingly cell proliferation and adhesion." (PMID 28698765, 2017). "In the case of BET inhibitor JQ1, we also show that co‐drugging suppresses the NGFRHigh state in BRAF‐mutant melanoma xenografts treated with dabrafenib." (PMID 28069687, 2017). "While selective BRAF inhibitors are efficacious in BRAFmut melanoma, they have limited efficacy in BRAFmut CRC patients." (PMID 27999210, 2017).
melanoma (continued). "Recently, we have demonstrated that DET- and/or DETD-35-induced reactive oxygen species (ROS) production in mouse mammary cancer cells TS/A, or human BRAF mutant A375 melanoma cells resulting in cancer cell apoptosis." (PMID 28915644, 2017). "The combination of these two effects is likely to render leukemia cell growth less-sensitive to EPZ-5676, an effect that is analogous to the hypermorphic BRAF mutants conferred resistance to targeted therapy in melanoma." (PMID 28231254, 2017). "Our results are consistent with the notion that in addition to activation of the MAPK pathway by mutations of BRAF or NRAS in roughly 60% of melanoma patients, also over-activation of the FGF axis contributes to melanoma growth." (PMID 29152117, 2017). "We reveal that RhoJ modulates the growth properties and apoptotic threshold of BRAF mutant melanocytes, accelerating both the formation of nevi and the growth and metastasis of melanoma tumors." (PMID 28753606, 2017). "Markers tested by NGS mainly provide information relevant for using targeted therapy (breast: HER2 IHC; colon: KRAS; lung: EGFR; and melanoma: BRAF)." (PMID 28371134, 2017). "It is well known that, at optimal dosage, BRAF inhibitors induce paradoxical proliferation in BRAFWT primary melanoma cells 32, and even at suboptimal dosage in some BRAFV600‐resistant melanoma cell lines, as it appears in reported experiments." (PMID 28573821, 2017). "This phenomenon has been widely reported for many targeted cancer therapies, such as for the BRAF inhibitors that can induce high levels of BRAF expression in BRAFi treated melanoma cells." (PMID 28099902, 2017). "For example, BRAF inhibitor-resistant melanoma cells which possess hyperactivation of ERK and AKT to overcome BRAF inhibition, yet they gradually lose autophagic proteins including Atg5 and AMPK while continuously exposed to BRAF inhibitor vemurafenib." (PMID 28629173, 2017). "Targeting upstream effectors of ERK with pharmacologic inhibitors yielded promising results and clinical trials with combined PI3K and BRAF inhibitors, reported to inhibit melanoma tumor growth in mice, are currently in progress." (PMID 28188308, 2017). "Selective BRAF inhibitors targeting the BRAFV600E mutant have been extensively studied and are effective in melanoma harboring this mutation." (PMID 27999210, 2017). "Although the mechanism of blood-brain transport is unclear, the response and improved survival curves in patients treated with BRAF inhibitors suggest some level of inhibitor penetrance in patients with active cranial melanoma metastases." (PMID 29179523, 2017). "Given the poor prognosis of BRAF melanoma and the rapid rate at which resistance develops and tumors progress, there is an urgent need to identify suitable combinations." (PMID 28085880, 2017). "In one study employing a murine melanoma model, 14 out of 16 recurrences were found to have mutated BRAF, so VSV-BRAF was used to successfully target the recurring tumors." (PMID 28751892, 2017). "Indeed, although NRAS or BRAF mutations represent the main force driving melanoma development, they are not “per se” sufficient since these mutations are also present in benign nevi, thereby highlighting the requirement of other factors to drive melanocyte transformation and melanoma development." (PMID 28491820, 2017). "Melanoma cells have been discussed to have a highly oxidative metabolism and thus treatment with BRAF or MEK inhibitors, increase oxidative stress within the cancer cell by upregulating ROS (as we show here)." (PMID 28595656, 2017). "Regardless, our results have clearly demonstrated the important role of reactivation of ERK in CD47 upregulation in melanoma cells by BRAF/MEK inhibitors." (PMID 29050218, 2017). "In this experiment, we exploit the inherent heterogeneous response of the A375 melanoma line to suboptimal BRAF inhibition as a model of immediate adaptive response." (PMID 28573821, 2017).
melanoma (continued). "In support of this idea, an increase in the expression of NOXA and BIM occurred upon treatment in both mutated BRAF and NRAS cell lines along with melanoma patient samples." (PMID 27086916, 2017). "Mutations leading to upregulation of the PI3K/AKT pathway have been identified in 22% of melanomas with acquired resistance to BRAF inhibition." (PMID 29100459, 2017). "The present study used a previously-established patient-derived orthotopic xenograft (PDOX) nude mouse model of BRAF V600E-mutant melanoma to determine the efficacy of rMETase in combination with a first-line melanoma drug, temozolomide (TEM)." (PMID 29156737, 2017). "We confirmed, using western blot and spectrophotometry, that Hsp90 or BRAF inhibitor-induced melanoma cell differentiation resulted in an upregulation of tyrosinase and melanin expression levels, in comparison to control cells." (PMID 28811486, 2017). "BRAF inhibition in melanoma, for example, has been shown to downregulate mir-216b expression, promoting autophagy." (PMID 29112174, 2017). "In this study, we treated one BRAF wild-type and two BRAF-mutant melanoma cell lines with the HDACis, SAHA and valproic acid, either alone, or in combination with the BRAF inhibitor, vemurafenib." (PMID 28596940, 2017). "In melanoma, CRISPR screens have looked for genes whose loss confers resistance to the BRAF inhibitor vemurafenib, identifying targets such as NF1, whose loss results in activation of NRAS, a recognized vemurafenib resistance mechanism." (PMID 28097822, 2017). "The BRAF inhibitors developed for the treatment of BRAF mutant melanoma are among the posterchilds for targeted therapy." (PMID 28694322, 2017). "Inhibition of mutated BRAF and MEK has been investigated in many clinical trials and is now one of the most preferred treatments of BRAF mutated melanoma." (PMID 28848761, 2017). "Time course experiments and a series of western blots were performed in a panel of BRAFV600E and BRAFWT/NRASmut human melanoma cells, which were incubated with BRAF and MEK1 kinase inhibitors." (PMID 28595656, 2017). "A median PFS of 14.9 months for the combination therapy compared to 7.3 months for vemurafenib (HR 0.54; 95% CI 0.41–0.71; P < 0.001) was reported in patients with BRAF mutant melanoma, with a favorable safety profile for the combination." (PMID 29100459, 2017). "One of the most common mutations leading to intrinsic BRAF resistance is loss of the phosphatase and tensin homolog (PTEN) gene, which occurs in up to 35% of melanomas." (PMID 29100459, 2017). "Pre-clinical and clinical trial studies developed the treatment of melanoma by inhibition of this signaling pathway target including using BRAF inhibitors; the upstream of ERK1/2." (PMID 28830513, 2017). "A number of studies link IQGAP1 to cancer through roles in tissue invasion, alterations in cell-cell junctions, angiogenesis, cell proliferation and more recently, resistance to a BRAF inhibitor used to treat melanoma." (PMID 29240845, 2017). "Analyses of tumor biopsies have revealed multiple resistance mechanisms in 50–80% of BRAF inhibitor-resistant melanoma patients." (PMID 28431544, 2017). "Here, we report that subtoxic concentrations of this compound significantly reduced invasiveness of BRAF-V600D mutated WM115 and WM266.4 melanoma cell lines derived from the primary lesion and related skin metastasis of the same patient, respectively." (PMID 28107182, 2017). "Gadolinium-based nanoparticles and BRAF inhibitors concurrent with RT are being explored for melanoma brain metastases." (PMID 28245881, 2017).
melanoma (continued). "More importantly, this improved therapeutic effect was observed especially in melanoma cell lines and PDX models containing concurrently BRAF V600E mutation and EZH2 gain." (PMID 29202777, 2017). "Inhibition of EGFR or Src Tyrosine Kinases were also found to be effective in overcome BRAF inhibitor resistance in melanoma cells." (PMID 29113311, 2017). "In melanoma, Bfl-1 overexpression confers resistance to BRAF inhibitors, and siRNA-mediated knockdown of Bfl-1 induces cell death in melanoma cell lines but not non-malignant cells." (PMID 28594323, 2017). "By using SRM, they discovered a mechanism by which melanoma cells with BRAF mutation and PTEN loss can escape from BRAF inhibition." (PMID 28265552, 2017). "Previously, a BRAF-V600E-mutant melanoma obtained from the right chest wall of a patient was transplanted orthotopically in the right chest wall of nude mice to establish a PDOX model." (PMID 29156737, 2017). "Preservation of IFN signaling can protect melanocytes from becoming malignant and renders melanoma cells sensitive to BRAF inhibitors and immunotherapy." (PMID 28798748, 2017). "The present study provides extensive characterization of genomic subtypes based on mutations in BRAF, RAS, and NF1 by using a large dataset comprising mutation data for 1461 genes in 864 clinically annotated melanomas." (PMID 28267273, 2017). "We also used melanoma cells derived from patients whose tumors eventually relapsed from both BRAF/MEK inhibitors and immunotherapy treatment (MB1860)." (PMID 27086916, 2017). "The most common genetic mutation suitable for targeted therapy within the MAPK pathway, is located in the B-Raf proto-oncogene, serine/threonine kinase (BRAF) accounting for approximately 40–60% of all melanomas." (PMID 28350340, 2017). "A retrospective study of 27 patients treated with vemurafenib for their BRAF mutant melanoma that had metastasized to the brain reported intracranial ORR of 50% and extracranial ORR of 71%." (PMID 28993799, 2017). "While we have trained and tested our approach in the context of BRAF mutant melanoma, the approach itself is applicable to other types of cancers." (PMID 28085880, 2017). "Among 253 melanomas, 129 (51.0%) BRAF, 45 (17.8%) NRAS, 6 (2.4%) KIT, 4 (1.6%) GNAQ, 2 (0.8%) GNA11, 2 (0.8%) MAP2K1 and no MAP2K2 gene mutations were detected by the biochip assay." (PMID 28881731, 2017). "Intriguingly, antisense oligonucleotide–mediated skipping of exon 6 decreased MdmX abundance, inhibited melanoma growth, and enhanced sensitivity to BRAF inhibitors in human melanoma cell lines and melanoma patient–derived xenografts." (PMID 28973015, 2017). "Data reported from melanomas cells, demonstrated that oncogenic BRAF promotes melanoma metastasis and aggressiveness through the down-regulation of the cyclic GMP (cGMP)-specific phosphodiesterase PDE5A with interaction between RAS/RAF and cAMP pathway." (PMID 27738305, 2017). "Among 41 response-evaluable patients, 2 (5 %) patients with cutaneous melanoma (one with BRAF L597R mutant melanoma) had partial responses." (PMID 27650277, 2017). "BRAF inhibitors are of high interest for treating BRAF-mutant melanomas due to their selectivity and effectiveness." (PMID 28085880, 2017). "Melanomas of a “MITF‐high” phenotype usually respond well to BRAF inhibitor therapy, but these melanomas also contain subpopulations of the de novo resistance “AXL‐high” phenotype." (PMID 28606996, 2017). "The presence of BRAF mutation is also associated with enhanced and selective sensitivity to MEK inhibition in melanoma cells." (PMID 29179523, 2017). "We conclude that melanoma inflammatory niches adapt to and confer drug tolerance toward BRAF and MEK inhibitors early during treatment." (PMID 28450382, 2017). "In 452 patients, 182 (40.3%) melanomas were BRAF-mutant, 95 (21.0%) were NRAS-mutant, and 180 (39.8%) were wild-type (no BRAF mutation and no NRAS mutation); only 5 (1.1%) were both BRAF-mutant and NRAS-mutant." (PMID 29349077, 2017).